TMPRSS2 (transmembrane serine protease 2)
Diseases named in the same sentence as TMPRSS2 in open-access papers (continued):
Sharing a sentence is not in itself a finding about the gene and the disease.
viral infection (continued). "Additionally, we also demonstrated the co-localization of SARS-CoV-2 with hACE2 and serine transmembrane protein 2 (Tmprss2), an established receptor and recently known co-receptor for the viral infection, respectively 1, 43-46." (PMID 34335981, 2021). "Therefore, delivery of TMPRSS2 inhibitors during viral infections is likely a relatively safe strategy." (PMID 33969249, 2021). "Additionally, important elements involved in the activation of viral infection are proteases: transmembrane protease serine 2 (TMPRSS2), cathepsin B (CatB) and cathepsin L (CatL)." (PMID 34200951, 2021). "Moreover, we did not perform our assays in a clinically relevant system, where viral infection is dependent on TMPRSS2 and requires membrane fusion, thus facilitating syncytium formation." (PMID 34805783, 2021). "In particular, high expression levels of JARID1B, ACE2 and TMPRSS2 in human respiratory epithelium cells intimate that further investigation of the identified regulatory network could expand our understanding of the viral infection pathogenesis." (PMID 32726325, 2020). "TMPRSS2 is known to cleave the influenza A virus and knock out TMPRSS2−/− mice are resistant to infection, indicating the importance of this gene in the spread and pathogenesis of viral infection." (PMID 33101356, 2020). "Overall, ACE2 and TMPRSS2 mRNA are expressedin the same organs in males and females,suggesting that they could potentially contribute to viral infection of these organs." (PMID 32652001, 2020). "This difference may reflect selective destruction of TMPRSS2 positive pneumocytes in high relative to low viral infections and repopulation by pneumocytes." (PMID 33298930, 2020). "These suggest that TMPRSS2 is a promising target for viral infection therapy." (PMID 32376987, 2020). "Interestingly, TMPRSS2 is expressed widely in the human respiratory tract where epithelial cells are also targeted for viral infection." (PMID 29415501, 2018). "The dual role of TMPRSS2 in facilitating viral entry and influencing tumor progression makes it an attractive target for interventions that could benefit both cancer control and viral infection prevention." (PMID 40145441, 2025). "Viral infection further requires proteolytic cleavage of the S protein for subsequent fusion with cellular membranes, mediated by cellular proteases, the most common of which is transmembrane serine protease 2 (TMPRSS2) and is expressed in epithelial cells of the respiratory tract." (PMID 38230954, 2024). "Indeed, using a human lung cell line, we could confirm the importance of ACE2 for virus infection; however, here an overexpression of TMPRSS2 greatly increased virus infectivity." (PMID 36979408, 2023). "The fact that TMPRSS2 displays an important role in SARS-CoV-2 entry into host cells suggests that the modulation of its expression by anti-androgenic therapies may provide an alternative strategy to treat viral infection." (PMID 36834705, 2023). "Similar results of significantly reduced host cell entry (viral infection) were evident when WT-spike-rVSV pseudovirions were generated in the presence of other spike targeting antibodies converted into FuG1 antibodies and were tested using TMPRSS2- 293-ACE2cells." (PMID 35138160, 2022). "Therefore, all these human enzymes, including CTSL, TMPRSS2, and furin, could be involved in the viral infection process, and are most likely to play complementary or compensatory roles in different human tissues." (PMID 35668062, 2022). "Consequently, inhibiting TMPRSS2 activity is a promising strategy to block viral infection." (PMID 35163273, 2022). "Thus, the expression of ACE2 and TMPRSS2 is indispensable for viral infection in cells." (PMID 33401657, 2021). "However, the distribution of ACE2 and TMPRSS2 expression in human organ systems associated with viral infection has not been comprehensively characterized in the literature." (PMID 35602214, 2021).
viral infection (continued). "TMPRSS2 is more largely expressed in human tissue than ACE2, whereas single-cell RNA sequencing (scRNAseq) in human respiratory tissue has shown a co-expression of ACE2 and TMPRSS2 in lungs, heart, and kidneys, which would indicate that these cells are strongly susceptible to viral infection." (PMID 33312128, 2020). "Specifically, A549-hACE2+TMPRSS2 cells challenged with SARS-CoV-2 lentiviral pseudoparticles pre-treated with FH, significantly reduced viral infection by ~25%." (PMID 40895576, 2025). "As regards the mechanisms of the viral infection, it is known that SARS-CoV-2 uses the ACE2 receptor for entry and TMPRSS2 for S protein priming." (PMID 40361463, 2025). "The viral infection depends on the expression of angiotensin-converting enzyme 2 (ACE2) and TMPRSS-2 transmembrane protease, which are the main cellular factors involved in viral entry." (PMID 40106491, 2025). "Meanwhile, transmembrane protease serine 2 (TMPRSS2), a host surface protease, cleaves and activates the virus’s S protein, thus promoting viral infection." (PMID 38892254, 2024). "Transmembrane protease serine 2 (TMPRSS2) modifies SARS-CoV-2 to facilitate cellular access, making ACE2 and TMPRSS2 crucial targets for preventing virus infection." (PMID 39064906, 2024). "Expression of ACE2, TMPRSS2, and AGTR1 was analyzed, and the impact of viral infection on ACE2 expression, vascular inflammation, and vascular morphology was assessed." (PMID 38576426, 2024). "Transmembrane protease, serine 2 (TMPRSS2) along with furin initiate the activation of the spike protein, and this activation process is one of the very important steps in the viral infection, pathophysiology, and its transmission within the host body." (PMID 36839773, 2023). "We observed robust reduction in viral infection upon treatment with increasing concentrations of NSC80997 in all cell lines, with IC50 values ranging from 4.3 μM for Caco-2 to 1.4 μM for Vero-TMPRSS2 and Huh-7.5 cells." (PMID 36804936, 2023). "Based on the differential expression of virus infection-related genes (ACE2, TMPRSS2, CTSB, CTSL), a recent study claimed that endometrial tissue is likely safe from SARS-CoV-2 cell entry but susceptibility increases with age." (PMID 37142998, 2023). "A549-hACE2+TMPRSS2 cells, challenged with SARS-CoV-2 lentiviral pseudoparticles that were pre-treated with C1q or C4BP, reduced viral infection by ~60% and ~17%, respectively, compared to the control (A549-hACE2+TMPRSS2 cells + SARS-CoV-2 pseudoparticles)." (PMID 37376569, 2023). "The ACE2, TMPRSS2, and Furin molecules became notorious during the SARS-CoV-2 pandemic, since their fundamental role in the mechanism of the virus infection was perceived." (PMID 37568724, 2023). "Two human genes related to viral infection have been identified, ACE2 and TMPRSS2, whose protein products are directly involved in the viral life cycle." (PMID 36012436, 2022). "Further, transmembrane serine protease 2 (TMPRSS2), which locates in proximity to ACE2, primes viral infection through enzymatic cleavage of S protein." (PMID 35958432, 2022). "Moreover, we have found increased co-expression of TMPRSS2-TMPRSS4 in gastrointestinal cancers suggesting that SARS-CoV-2 viral infection known to be mediated by this protease pair might facilitate the effects of viral infection in GI cancer patients." (PMID 35970857, 2022). "In SARS-CoV-2 infection, AAT suppresses the key protease Transmembrane Serine Protease 2 (TMPRSS2), which cleaves the viral spike (S) protein to facilitate infection, and thus inhibits viral infection." (PMID 34066804, 2021). "Our observations that urinary ACE2 and TMPRSS2 do not associate with AKI or disease severity suggest that urinary clearance of SARS-CoV-2 N more reflects systemic inflammation due to viral spread rather than renal cell death by direct viral infection of the kidneys." (PMID 34113632, 2021).
viral infection (continued). "EVs can be used therapeutically to fight viral infection, demonstrated clearly by a recent study showing that engineered EVs containing ACE2 and TMPRSS2 sequestered SARS‐CoV‐2 spike pseudovirus and prevented infection." (PMID 34188786, 2021). "Among several proteins implicated as potential targets, host cell membrane proteins; transmembrane protease serine 2 (TMPRSS2) and angiotensin-converting enzyme 2 (ACE2) play a central role in viral infection and entry." (PMID 34647577, 2021). "To confirm that the expression of ACE2, TMPRSS2, and FURIN in adult human inner ear tissue facilitates viral infection, we exposed explanted human vestibular tissue to conditioned media (“mock”) or SARS-CoV-2." (PMID 34870285, 2021). "TMPRSS2 inhibition is a safe and efficient treatment of viral infections (MERS-CoV, SARS-CoV, SARS-CoV-2, several H1N1 subtypes of influenza A viruses, and Asian H7N9 influenza virus) that utilize TMPRSS2 for implantation in host cells." (PMID 34445373, 2021). "The upper respiratory tract is the initial site of viral infection; two proteins critical for the viral entry, ACE2 and TMPRSS2 are highly expressed in nasal goblet cells and ciliated cells of human airways." (PMID 33909679, 2021). "However, 8P9R could significantly inhibit SARS-CoV-2 in both Vero-E6 and Calu-3 cells, which suggested that 8P9R not only inhibited the viral infection through endocytic pathway in Vero-E6 cells but also inhibited viral entry through TMPRSS2-mediated pathway in Calu-3 cells." (PMID 33750821, 2021). "In order to confirm the activity of TMPRSS2 in the HEK293T-ACE2-TMPRSS2 cell line, we treated the cells with different doses of camostat mesylate for 24 h and measured the level of viral infection." (PMID 35126106, 2021). "Cytotoxic lymphocytes, including CD8+ T cells and NK cells, are key early responders to virus infections, and these are the cells whose baseline levels were identified here as significantly reduced in lung tissue with elevated ACE2 and TMPRSS2 expression." (PMID 32873611, 2020). "Our findings clearly indicate that nafamostat mesylate, the most effective TMPRSS2 inhibitor so far reported, potently inhibits SARS-CoV-2 S protein-mediated fusion in a cell fusion assay system and viral infection in vitro in a cell-type-dependent manner." (PMID 32532094, 2020). "When h3ACs were treated with camostat mesylate, a serine protease inhibitor active against TMPRSS2, SARS-CoV-2 entry and progression were partially blocked, corroborating that the activity of TMPRSS2 is required for viral infection of hAT2 cells." (PMID 33142113, 2020). "In conclusion, we first demonstrated that TMPRSS2 and MSPL facilitate the replication of the animal coronavirus PEDV and play a significant role in viral infection by promoting cell–cell fusion and virus–cell fusion." (PMID 28524070, 2017). "The placenta possesses several structural and immunological barriers against viral infections, the SARS-CoV-2 detection in placental tissues has raised concerns regarding possible alternative viral entry mechanisms beyond the canonical ACE2/TMPRSS2-mediated pathway." (PMID 41319265, 2025). "The absence of TMPRSS2 affected key sites of viral infection and dissemination in the airways, accompanied by less severe immunopathology." (PMID 39858469, 2025). "To confirm these findings in the context of authentic virus infection, we examined the effect of GBP5 or GBP5-C583A overexpression on S protein processing and infection with SARS-CoV-2 in HEK 293T cells expressing the SARS-CoV-2 co-receptors ACE2 and TMPRSS2." (PMID 38746287, 2024). "Lactoferrin might also protect females from viral infection by reducing the expression of the ACE2, together with the down expression of TMPRSS2." (PMID 38836262, 2024).
viral infection (continued). "The host immune targets such as TLR7, IRF7, IRF5, and IL6, which are involved in the immune response against viral infections, and the sex-specific targets such as AR and ESSR were taken to investigate any possible link with the SARS-CoV-2 host receptors ACE2 and TMPRSS2." (PMID 36992366, 2023). "Furthermore, we recently showed that a RG4 structure within Tmprss2 can significantly repress Tmprss2 translation and prevent SARS-CoV-2 entry, exemplifying the regulation and importance of RG4 on host factors and virus infection." (PMID 36701392, 2023). "Viral infection by SARS-CoV-2 to host cells occurs through binding to the angiotensin-converting enzyme 2 (ACE2) receptor on the cell surface, followed by activation of the spike (S) protein by transmembrane serine protease 2 (TMPRSS2)." (PMID 37646728, 2023). "Consistent with TMPRSS2-dependent plasma membrane fusion, IFITM1 was found to potently and significantly inhibit infection of early-lineage viruses (Wuhan-Hu-1 and VIC) and VOCs Alpha and Delta in both PV and live virus infections." (PMID 36693093, 2023). "As a consequence, these additional residues may therefore affect TMPRSS2-mediated SARS-CoV-2 spike protein priming and viral infection." (PMID 38455847, 2023). "Host proteases, including furin, TMPRSS2, and CTSL work together to modulate coronavirus S protein-mediated cell fusion, and disturbing the activity of these proteases will effectively inhibit virus infection and proliferation." (PMID 37196033, 2023). "Amongst evaluated compounds, compound 14, which was the most effective inhibitor of viral infection despite it not being a potential TMPRSS2 inhibitor, possessed comparable IC50 values to those of pentamidine for the inhibition of thrombin and factor Xa." (PMID 37243257, 2023). "We found that viral infection was strongly inhibited by blocking endosomal entry with chloroquine in VeroE6, lacking TMPRSS2 expression." (PMID 36298757, 2022). "Furthermore, transmembrane protease serine 2 (TMPRSS2) is a host surface protease that cleaves and proteolytically activates its S protein, which is necessary for viral infection." (PMID 36499094, 2022). "In the present study, SARS-CoV-2 RNA replication was detected in fresh human cornea and conjunctiva 24 hours after viral infection, both tissues expressing SARS-CoV-2 receptor and activators ACE-2, TMPRSS2, and Cathepsin B/L with variable amount and localization." (PMID 35231027, 2022). "It is known that MSCs are negative for both ACE2 and TMPRSS2 genes, suggesting that there is no likelihood of viral infection in the cells." (PMID 34769246, 2021). "The results suggest the expressions of ACE2 and TMPRSS2 proteins in HPAEpiC cells maintains stable, which are not dependent on viral infection and culture conditions." (PMID 33173719, 2021). "This compound also failed to change the viral infection in ACE2/TMPRSS2-expressing HEK cells after 24 h of treatment." (PMID 35126106, 2021). "Moreover, there are no obvious changes in the expression levels of ACE2 and TMPRSS2 in both cell types after viral infection, suggesting the less effects of viral infection on the protein levels of ACE2 and TMPRSS2 in host cells." (PMID 33173719, 2021). "Therefore, to curb virus infection, both promoting type I IFN signaling to boost innate immunity and prevention of virus entry by inhibiting PARP1, ACE2 or TMPRSS2 are safe options." (PMID 34445373, 2021). "During viral infection, the spike (S) protein of CoV-2 interacts with ACE2, and the cellular transmembrane serine protease 2 (TMPRSS2) mediates the viral envelope to host cell membrane fusion, leading to the release of viral nucleocapsid into the cytoplasm of host cells." (PMID 34818337, 2021). "Repression of the histone modifier could alter the cell’s response to viral infection by involving ACE2 and TMPRSS2 genes." (PMID 34445368, 2021).
viral infection (continued). "In addition, we also profiled the expressions of the known cofactors of ACE2, i.e., TMPRSS2, FURIN, and NRP1, which also play roles during the viral infection and are also conserved between human and the mammalian species investigated above." (PMID 33392409, 2021). "Afterward, we found that SARS‐CoV‐2 infection per se results in ACE2 and TMPRSS2 increased gene expression in VERO E6‐cell, which could be generating a cycle of virus infection in host cells." (PMID 33463909, 2021). "Here, we discuss, based on published reports, PARP1-dependent TMPRSS2 regulation through auto-poly(ADP-ribosyl)ation, since viral infection stimulates pro-inflammatory pathway via the induction of iNOS and cytokines (IL6), increases the ROS in cells, and causes ssDNA damage." (PMID 34445373, 2021). "We also show that IL22 reduces the expression of viral entry receptors (e.g. ACE2, TMPRSS2, DPP4, CD46 and TNFRSF14), increases the expression of anti-viral proteins (e.g. RSAD2, AOS, ISG20 and Mx1) and, consequently, reduces the viral infection of neighboring cells." (PMID 34045640, 2021). "Further, the presence of PS receptors did not enhance virus infection in the presence of TMPRSS2, suggesting that this route of virus entry is independent of PS receptor utilization." (PMID 34797899, 2021). "The virus infection occurs through the binding of viral Spike proteins (S-protein) to human cells utilizing a 2-step process that involves Angiotensin-Converting Enzyme-2 (ACE2) and Transmembrane Serine Protease (TMPRSS)-2." (PMID 34638539, 2021). "So far it is not known, if other surface receptors and molecules apart from ACE2, TMPRSS2 and TMPRSS4 exist that might mediate viral infections in intestinal epithelial cells via the basolateral side." (PMID 33608656, 2021). "In contrast, the TMPRSS2 inhibitors aprotinin and camostat mesilate did not significantly inhibit viral infection (P > 0.1)." (PMID 33723017, 2021). "Many of those initial approaches were aiming to identify existing compounds to prevent viral infection by either targeting mechanisms involving the viral receptor ACE2 (angiotensin converting enzyme 2), the TMPRSS2 transmembrane protease serine 2, or clathrin-mediated endocytosis." (PMID 34293006, 2021). "After virus infection, we also measured the levels of ACE2 and TMPRSS2 in the VERO E6 cell line." (PMID 33463909, 2021). "Another study showed that the intracellular TMPRSS2 has the ability of specific recognition and binding with the S protein of SARS-CoV-2, which plays an important role in the process of virus infection and transmission, ending in the inflammatory cytokine storm." (PMID 33014532, 2020). "Conversely, the protease required for viral entry, TMPRSS2, was reduced upon viral infection but was not modulated by viral dose, nor were ribosomal proteins (RPL4, RPS6)." (PMID 32898168, 2020). "Thus, repression of histone modifiers can adjust the cell response to viral infection by engaging a complex regulatory mechanism involving ACE2 and TMPRSS2 genes." (PMID 32726325, 2020). "Furthermore, our results also highlighted that Vero/TMPRSS2 and Vero/MSPL cells can significantly enhance the isolation of PEDV from the clinical tissue samples as well as promote viral infection and replication by cell-cell fusion." (PMID 32471322, 2020). "Given that the dynamics of the virus infection have not been fully revealed, it is still uncertain to what extent a high level of TMPRSS2 alone, without the change of ACE2, would lead to a higher infection efficiency." (PMID 32973879, 2020). "Although TMPRSS2 alone did not mediate viral infection, co-expression of TMPRSS2 with ACE2 resulted in enhanced infectivity." (PMID 32404436, 2020). "It is thus highly likely that TMPRSS2 alone does not increase permissiveness to SARS-CoV-2 when the ACE2 levels are not sufficient for viral infection." (PMID 32969768, 2020).